MTND6P4 (MT-ND6 pseudogene 4)
Gene: Processed pseudogene on chromosome 5 (134,924,123 to 134,924,644, forward strand). Ensembl gene ENSG00000249119.
Diseases named in the same sentence as MTND6P4 in open-access papers:
MTND6P4 is named in the same sentence as 3 diseases in open-access papers, as found by Europe PMC text mining. Sharing a sentence is not in itself a finding about the gene and the disease. The quoted sentences say what the papers report.
breast tumours (1 paper, 2022). "MTND6P4 and MIR3193 are frequrently methylated in primary breast tumours tumurs (9/19, 16/19)." (PMID 35058523, 2022). "In our study, MIR3193, MTND6P4 and CTD-2023M8.1 were frequently methylated in a cohort of non-metastatic primary breast tumours and infrequently methylated in BBM." (PMID 35058523, 2022).
tumour (1 paper, 2022). "Of these, the promoter regions of three genes (MIR124-2, RP11-713P17.4, and NUS1P3) were hypermethylated in BBM and three genes (MIR3193, CTD-2023M8.1 and MTND6P4) were hypomethylated in BBM relative to the primary tumours." (PMID 35058523, 2022). "It is possible that epigenetic dysregulation of MTND6P4 may contribute to an energy shift towards glycolysis leading to acidosis with microenvionment changes that provide powerful growth advantages and invasive potential to the tumour cell." (PMID 35058523, 2022). "We could bisulphite convert, amplify and analyse the promoter regions for RP11-713P14.4, MIR3193, MTND6P4 and CTD-2023M8.1 in these corresponding primary tumours." (PMID 35058523, 2022). "MTND6P4 may regulate its parental gene MTND6 and hypomethylation and subsequent overexpression of MTND6P4 may lead to changes in oxidative phosphorylation activies, glycolysis and brain microenvironment contributing to growth advantages to tumours via upregulation of MTND6." (PMID 35058523, 2022). "Three non-protein coding genes MIR3193, MTND6P4 and CTD-2023M8.1 are hypomethylated in BBM compared to primary tumours and normal breast tissues." (PMID 35058523, 2022).
MTND6P4 also shares sentences with these, for which no sentence is quoted: cancer (1 paper).